RPL3 (ribosomal protein L3)
Diseases named in the same sentence as RPL3 in open-access papers (continued):
Sharing a sentence is not in itself a finding about the gene and the disease.
malaria (1 paper, 2016). Malaria is a serious and sometimes fatal disease caused by a parasite that commonly infects a certain type of mosquito which feeds on humans. "Separating antigenic protective antigens (the “wheat”) from dispensable antigens such as PyMDH and P. yoelii ribosomal protein L3 (the “chaff”) represents a major hurdle to our understanding of the Plasmodium-specific T cell repertoire and to development of effective subunit vaccines for malaria." (PMID 27070430, 2016).
Obesity (1 paper, 2025). Accumulation of substantial excess body fat. "Surprisingly, while RPL3 alleviated obesity, it failed to improve serum cholesterol parameters." (PMID 40851863, 2025).
parasitemia (1 paper, 2021). "Vaccination with four of the six antigens (HT, RPL3, ETRAMP10.3 or SPATR) did neither induce sterile protection nor a statistically significant delay in the time to 1% parasitemia in both BALB/c and CD-1 mice." (PMID 34252120, 2021).
prostate carcinoma (1 paper, 2018). A carcinoma that arises from epithelial cells of the prostate gland. "In other cases, expression patterns appeared to be dominated by the differential relative expression of one or two RPTs, as seen with prostate cancer Cluster 2 and HCC Cluster 3, both of which possess tumors that overexpress RPL8 and under-express RPL3." (PMID 29530001, 2018).
cancer (27 papers, 2014 to 2025). A tumor composed of atypical neoplastic, often pleomorphic cells that invade other tissues. "Three of these four genes, BRCA1, PSMD4, and RPL3, are reported as cancer genes, and STAT1 is associated with both cancer and AIDs." (PMID 40429780, 2025). "The large ribosomal protein, RPL3, is also misregulated in cancer and low expression is associated with invasion (Pecoraroet al., 2019)." (PMID 38628976, 2023). "Of the recurring RPT expression patterns discovered by t-SNE, the pattern associated with RPL3 down-regulation occurred most frequently and involved tumors from nine cancer cohorts." (PMID 29530001, 2018). "There is emerging evidence for extra-ribosomal functions of the small ribosomal protein RPS3 and the large ribosome protein RPL3 in regulating cell invasion in cancer cells." (PMID 38628976, 2023). "Recently, our group has developed novel biodegradable nanoparticles (NP) as a platform to deliver the conventional drug 5-FU and the proapoptotic protein rpL3 aimed to enhance drug-induced cancer cell cytotoxicity." (PMID 28085118, 2017). "The cytotoxic effects of 5-FU and L-OHP including DNA damage, changes in cell cycle and apoptosis, failed to occur after the loss of rpL3 leading to cancer progression." (PMID 25473889, 2014). "In addition, snoRA51 enhanced cancer stem cell-like properties via the RPL3/NPM1/c-MYC pathway." (PMID 41510246, 2025). "Specifically, genes like PPARD, RPL3, and STAT1, which overlapped in both our epigenomic and transcriptomic analyses, are highly interconnected across AIDs and cancer." (PMID 40429780, 2025). "The significantly overexpressed sEV proteins in the BC plasma-derived UCT isolates were ALB, COL1A1, CSN1S1, EEF1A2, and RPL3; and the C1S, C5, C7, and CFHR2 sEV proteins in the UCT isolates were the most downregulated proteins in the BC plasma compared to the non-cancer control." (PMID 37895140, 2023). "Consistently, RPL3-mediated positive regulation of p21 expression via ERK (extracellular-signal-regulated kinase) activation results in promotion of apoptosis as well as reduction of proliferation and migration of these cancer cells." (PMID 30105457, 2018).
tumor (25 papers, 2002 to 2025). "Consistently, the protein levels of Ki67 (a proliferation marker), c-Myc (a stemness marker), and RPL3 (a ribosomal protein) were decreased in the tumor of mice injected with shMRPS27 knockdown MDA-MB-231 cells compared with the control cells." (PMID 38617541, 2024). "Although RPL3 induces G1 cell cycle arrest through the formation of protein complexes and inhibits tumor progression, most ribosomal proteins act as tumor promoters." (PMID 38977703, 2024). "In particular, the rpL3 mRNA amount decreases with malignant progression and the intensity of its expression is inversely related to tumor grade." (PMID 28085118, 2017). "Tumor proliferation, expressed as the ratio of Bcl-2 mRNA copy number to that of Bax, is found to be inversely proportional to the decrease of rpL3 gene expression and increased with tumor grade." (PMID 28085118, 2017). "A correlogram showed that RPL3, RPL12, and PTEN, whose coefficients of risk score were <0, had negative correlations with risk score, stromal score, immune score, and ESTIMATE score and positive relationships with tumor purity." (PMID 38137116, 2023). "The fact that relative down-regulation of RPL3 occurred in these tumor clusters with predictable expression of 11 other RPTs suggests that RPL3 may be acting in concert with these other identified RPs to exert its effects." (PMID 29530001, 2018). "In addition, the ectopic expression of rpL3 either in untreated cells or treated cells induced γ-H2AX formation strongly suggesting that rpL3 exterts itself cytotoxic effects leading to increase the susceptibility of tumor cells to chemotherapy." (PMID 25473889, 2014). "The results showed that RPL3 had higher expression levels in tumor compared with non-tumor tissues in more than half the clinical cohorts (57.1%)." (PMID 35191375, 2022). "Comprehensive comparisons of the expression of RPL3 between tumor and non-tumor tissues were conducted using seven clinical cohorts with available expression profiles of both tumor and non-tumor tissues." (PMID 35191375, 2022). "Among them, ACAA1, GART, PDE9A, RPL3, TUBA1A, and TUBG1 gene products interact with several proteins known to be involved in the PRAD pathway and particularly important for apoptosis inhibition and tumor growth." (PMID 33712625, 2021). "coli), RPLP0 (tumor progression, invasion, metastasis), RPS5, RPL9, RPS14, RPS2, RPL3, and RPL23." (PMID 34445327, 2021). "Our findings of RPL-3 to be primarily expressed in neoplastic and not stromal PC cells support the idea of specific tumor effects by inhibition." (PMID 29190795, 2017). "RNU43, which was lower in tumours with a poorer prognosis (although not statistically significantly), mapped to an intronic region of H. sapiens ribosomal protein L3 (RPL3, RefSeq NM_001033853.1 and NM_000967.3)." (PMID 21407217, 2011). "Unlike RPL3 and RPS4X, RPL13’s role in tumor development is less clear." (PMID 29530001, 2018).
infection (5 papers, 2020 to 2025). The state of being infected such as from the introduction of a foreign agent such as serum, vaccine, antigenic substance or organism. "Infection of cells with MHV particles caused accumulation of a β-globin NMD reporter mRNA as well as increased levels of the natural NMD target rpL3 mRNA, which encodes ribosomal protein L3 of the 60S ribosomal subunit." (PMID 32699064, 2020). "Initially, the presence of ribosomes and specific ribosomal subunits such as RPS6, RPS16, and RPL3 and viral mRNA within these sites indicated compartmentalization of translation during infection." (PMID 38421168, 2024). "In contrast, the biological processes downregulated with infection include ribosomal biogenesis (Rpl3, Rpl37, Rps5, Rpl11, Rplp1, Rpl28, Rpl19, Rps28, Rps14)." (PMID 35789215, 2022).
hematologic malignancy (1 paper, 2022). "Homoharringtonine, another drug used in hematologic malignancy, can be repurposed against RPL3 dysregulation (CMap score 100)." (PMID 36293493, 2022).
RPL3 also shares sentences with these, for which no sentence is quoted: ovarian carcinoma (3 papers); antiphospholipid syndrome (1); Arrhythmia (1); B-cell lymphoma (1); bladder cancer (1); cardiac hypertrophy (1); cardiomyopathy (1); cardiovascular disease (1); Cognitive impairment (1); depression (1); Diamond-Blackfan anemia (1); hematological cancer (1); iron deficiency (1); lipid metabolism disorders (1); Liver Dysfunction (1); Myelodysplasia (1); neuroblastoma (1); neurodegenerative disease (1); ovarian adenocarcinoma (1); paraganglioma (1); pheochromocytoma (1); thymoma (1).